COL5A2 (collagen type V alpha 2 chain)
Diseases named in the same sentence as COL5A2 in open-access papers (continued):
Sharing a sentence is not in itself a finding about the gene and the disease.
lung carcinoma (6 papers, 2015 to 2022). "Furthermore, COL6A3 (q = 3.1 × 10−4, COAD) and COL5A2 (q = 1.5 × 10−4, LUAD) mutations are significantly associated with a high mutation density in colorectal and lung cancer, respectively." (PMID 26352260, 2015). "The results indicated that the expression of COL5A2 and EPHB2 was obviously elevated in lung cancer tissue." (PMID 34419075, 2021). "The results showed that the expression levels of COL5A2 and EPHB2 were obviously upregulated in lung cancer tissue compared with normal tissue." (PMID 34419075, 2021). "The results showed that higher levels of COL5A2 and EPHB2 was correlated with worse survival status of lung cancer patients." (PMID 34419075, 2021). "COL5A2, MXRA5, and VCAN coexpressed with THBS2 may have significant oncogenic functions in both breast and lung cancers." (PMID 27513329, 2016).
pancreatic cancer (5 papers, 2020 to 2023). "Among them, one novel miRNA (hsa-mir-4772) and two novel genes (COL12A1 and COL5A2) associated with pancreatic cancer have great potential to be used as prognostic factors and therapeutic targets for this tumor." (PMID 34094925, 2021). "TME rearrangements in OS have been correlated with chemotherapy-resistant phenotypes, whereas a survival gene signature based on the expression of collagen genes Col3a1, Col4a1, and Col5a2 is correlated with glioblastoma and pancreatic cancer aggressiveness." (PMID 36831562, 2023). "Although the upregulation of COL12A1 and COL5A2 has not been experimentally shown in pancreatic cancer, their abnormal overexpression has been experimentally shown in other cancer types." (PMID 34094925, 2021).
liver fibrosis (4 papers, 2015 to 2024). "It was shown that a lack of collagen VIII reduces myofibroblast differentiation and fibrosis in mouse hearts, and that COL8A1 and COL5A2 are dysregulated in progressing liver fibrosis in rodents." (PMID 39466591, 2024). "Furthermore, the protein–protein interaction (PPI) network analysis based on the STRING database and GOIs provided insights into the functional relationships among key proteins in liver fibrosis, such as Col1a2, Col5a2, MMP9, Col4aa, Col27a1, and Col5a3." (PMID 38874114, 2024). "HQD down-regulated the expressions of PDGFra, PDGFrb, PDGFb, PDGFd, COL1A1, COL1A2, COL5A2 and THBS1, and TGF-β and PDGF signaling pathways in the DMN-induced liver fibrosis in rats." (PMID 26691002, 2015). "Ten DEGs including PDGFra, PDGFrb, PDGFb, PDGFd, COL1A1, COL1A2, COL5A2, ITGA5, THBS1 and IL1R1, closely related to liver fibrosis, were chosen for the real-time qRT-PCR analysis." (PMID 26691002, 2015).
tongue squamous cell carcinoma (4 papers, 2020 to 2023). A squamous cell carcinoma that arises from the tongue. "Reversely, COL5A2 may be a favorable factor for the prognosis of tongue squamous cell carcinoma." (PMID 32819300, 2020).
invasive ductal carcinoma (3 papers, 2020 to 2021). "Consistent with our data, COL5A2 expression itself is upregulated in epithelial cells of breast invasive ductal carcinoma compared to DCIS." (PMID 34565423, 2021). "COL5A2 related to extracellular matrix remodeling was up-regulated during the development from ductal carcinoma in situ to invasive ductal carcinoma, leading to BC progression." (PMID 33439992, 2021). "As an important molecule, COL5A2 is associated with remodeling of the ECM and is differentially expressed between in situ ductal carcinoma and invasive ductal carcinoma." (PMID 33282565, 2020).
ischemic heart disease (3 papers, 2013 to 2020). "In the long term, Col5a2 may represent a new prognostic or therapeutic target for patients suffering ischemic heart disease." (PMID 23574622, 2013).
lung adenocarcinoma (3 papers, 2021 to 2024). A carcinoma that arises from the lung and is characterized by the presence of malignant glandular epithelial cells. "Additionally, upregulation of COL5A2 was observed in lung adenocarcinoma compared to normal lung cells." (PMID 34299042, 2021). "Survival analysis shows that COL5A2 and SERPINB5 are significant for identifying lung adenocarcinoma and are considered biomarkers of lung adenocarcinoma." (PMID 35846148, 2022).
mesothelioma (3 papers, 2022 to 2023). A usually malignant and aggressive neoplasm of the mesothelium which is often associated with exposure to asbestos. "Fluorescent immunostaining of human mesothelioma cell lines showed that sarcomatoid CRL-5946 cells expressed COL5A2 and SPARC dramatically higher compared to epithelioid CRL-5915 cells, while CRL-5915 cells expressed epithelial marker EpCAM specifically." (PMID 35046456, 2022). "The top four genes (COL5A2, ITGAV, SPARC, and ACTA2) associated with the strongest correlation with EMT Top50 mesenchymal genes were selected for further analysis, confirming their prognostic importance in mesothelioma and other solid tumors using the TCGA database of online platforms." (PMID 36901697, 2023). "Furthermore, it might be of interest to investigate the contribution of RNA editing in the increased expression of COL5A2, ITGAV, and SPARC genes, which is correlated with mesenchymal phenotype in mesothelioma." (PMID 36769192, 2023). "Besides a few sporadic studies, this may be the first study to identify COL5A2, ITGAV SPARC and ACTA2 as a panel of emerging EMT genes in mesothelioma." (PMID 35046456, 2022).
myocardial infarction (3 papers, 2022 to 2023). Gross necrosis of the myocardium, as a result of interruption of the blood supply to the area, as in coronary thrombosis. "A study involving diseased hearts showed that Col5a2 expression was increased in myocardial infarction samples compared to the control samples and played an excellent role in distinguishing myocardial infarction." (PMID 35964009, 2022). "Gene co-expression network revealed that COL5A2 shows predictive potential in myocardial infarction, which may be a new candidate marker for identifying and treating ischemic cardiovascular diseases." (PMID 37731513, 2023).
breast tumor (2 papers, 2008 to 2022). "Our module showed the breast tumor specific co-expression between PDGFRL and collagens COL3A1, COL5A2 and COL6A3." (PMID 18366601, 2008). "Among the shared upregulated genes in normal breast tissues and breast tumors, the expression of five genes unique to young women aged ≤40 years with BC (i.e., COL1A2, COL5A2, COL5A1, NPY1R, and KIAA1644) significantly affected the OS and RFS of patients with several tumor subtypes." (PMID 35741056, 2022).
carcinoid (2 papers, 2021). "The expression of COL1A2, COL3A1, COL5A2, ITGA5, and ITGB1 in SCLC, LCNEC, and typical carcinoid samples in the GSE1037 profile, as compared with normal samples, were determined using a GEO2R online analyzer (log FC>2 and adjusted P<0.05) and then compared to the data from our cohort." (PMID 34458147, 2021).
colon adenocarcinoma (2 papers, 2022 to 2023). "According to the analysis, COL5A2 was significantly upregulated in cancerous tissues, such as STAD, cholangiocarcinoma, thyroid cancer and colon adenocarcinoma." (PMID 37723519, 2023). "COL4A1 was involved in diabetic tubulointerstitial injury and COL5A2 participated in the progression of uterine fibroids and colon adenocarcinoma, although their functions were not fully understood for GDM development." (PMID 36544488, 2022).
Colorectal tumors (2 papers, 2015 to 2023). "Colorectal tumors co-express COL5A2 and COL11A1, with COL5A2 protein binding to DDR1 and upregulating the WNT/β-catenin and PI3K/mTOR signaling pathways." (PMID 36765749, 2023).
Ehlers-Danlos syndrome type IV (2 papers, 2013 to 2024). "COL1A2, COL3A1, COL5A2 are a group of collagen genes in which mutations are associated with several connective diseases such as the involvement of COL3A1 mutations in intracranial aneurysms and Ehlers-Danlos syndrome type IV with aortic and arterial aneurysms." (PMID 24079748, 2013).
gastric adenocarcinoma (2 papers, 2023). "Besides, COL5A2 expression was elevated in three common histological subtypes of GC, including intestinal, diffused, and mixed gastric adenocarcinomas, as compared with that in gastric tissues or mucosa in Wang, Cho, Chen, and DErrico datasets (Figures A1 and A2, P < 0.05)." (PMID 36712590, 2023).
abdominal aortic aneurysm (1 paper, 2022). Enlargement and ballooning of the vessel that supplies arterial blood to the abdomen, pelvis and legs. "In mouse model of Col5a2 haploinsufficiency, the severity of abdominal aortic aneurysms was significantly raised, inducing aortic arch ruptures and dissections." (PMID 35964009, 2022).
allergic asthma (1 paper, 2024). A asthma with a basis in a pathological type I hypersensitivity reaction. "Similarly, in eCRSwNP we detected an interaction of basal EpCs with pericyte COL5A2 and COL5A3, both of which have been reported to be differentially methylated in allergic asthma." (PMID 38444858, 2024).
Aortic dissection (1 paper, 2013). Aortic dissection refers to a tear in the intimal layer of the aorta causing a separation between the intima and the medial layers of the aorta. "However, mutations in Col5A2 have been associated with vascular disease, such as cervical artery dissection and aortic dissection." (PMID 23574622, 2013).
aortic root dilatation (1 paper, 2025). "The classic type of EDS, caused by mutations in the COL5A1 or COL5A2 genes, is characterized by thin, translucent skin, easy bruising, and joint hypermobility, as well as vascular fragility and predisposition to aortic root dilatation and dissection." (PMID 40110250, 2025).
atherosclerosis (1 paper, 2020). A disease characterized by the build-up of fatty material and calcium deposition in the arterial wall resulting in partial or complete occlusion of the arterial lumen. "Neither COL5A2 nor KRT 9 peptide immunization resulted in significant effects on atherosclerosis compared to controls." (PMID 32373127, 2020).
basal cell carcinoma (1 paper, 2025). A carcinoma involving the basal cells. "Three key genes, VCAN, COL4A1 and COL5A2, may be involved in multiple activated signalling pathways in basal cell carcinoma, and they are co-enriched in extracellular space, extracellular region and endoplasmic reticulum lumen, extracellular matrix." (PMID 40386063, 2025).
breast invasive carcinoma (1 paper, 2023). "TCGA analysis of TGF-β target genes (e.g., COL1A1, COL3A1, COL5A2, COL6A1, COL6A3, TIMP1, and CTGF) further identified overactivation of TGF-β signaling pathway in a broad spectrum of solid tumors, in particular in breast invasive carcinoma and pancreatic adenocarcinoma tissues." (PMID 37328484, 2023).
cardiac hypertrophy (1 paper, 2022). "Our analysis indicated that Col5a2 is likely to be upregulated during the development of myocardial hypertrophy." (PMID 35964009, 2022).
Classical Ehlers-Danlos syndrome (1 paper, 2019). "Classical Ehlers-Danlos syndrome (cEDS) is a dominant inherited connective tissue disorder mainly caused by mutations in the COL5A1 and COL5A2 genes encoding type V collagen (COLLV), which is a fibrillar COLL widely distributed in a variety of connective tissues." (PMID 30716086, 2019).
COVID-19 (1 paper, 2023). A disease caused by infection with severe acute respiratory syndrome coronavirus 2. "The genes associated with EDS or COVID-19 severity are distributed on all chromosomes (except for Y and 8, 13, 16, 20 for COVID-19) with clusters at 2q32.2 (COL5A2/COL3), 3p24.1 (SCN5/10/11A), 11q23.3 (SCN2/4B), and 21q22.3 (COL6A1/A2) for EDS and at 3p22.2 (CCR1/5-CXCR6) for COVID-19 (column L)." (PMID 37504295, 2023).
Ehlers-Danlos syndrome types I (1 paper, 2010). "Finally, mutations in the COL5A1 and COL5A2 genes that encode the chains of type V collagen cause Ehlers-Danlos syndrome types I and II, which are characterized, among other defects, by skin laxity, a feature of the Crtap-/- mice." (PMID 20485499, 2010).
head and neck cancer (1 paper, 2023). A primary or metastatic malignant neoplasm affecting the head and neck. "The results indicated that highly-expressed COL5A2 appeared in 18 of 20 tumor types, especially in breast, gastric, colorectal, and head and neck cancers, which was consistent with the findings of several previous studies." (PMID 36712590, 2023).
ischemic cardiomyopathy (1 paper, 2013). Ischemic cardiomyopathy is a cardiomyopathy in which a weakness in the muscle of the heart due to inadequate oxygen delivery to the myocardium with coronary artery disease being the most common cause. "To explore the potential pathophysiological role of Col5A2 in humans, we analyzed publicly available microarray data acquired from cardiac tissue samples of patients with ischemic cardiomyopathy and controls." (PMID 23574622, 2013).
joint disease (1 paper, 2019). "Therefore, collagen dysfunction could lead to bone and joint disease including OA.COL24A1, COL5A2, COL3A1, COL6A1 are members of the collagen gene family." (PMID 30941059, 2019).
lymph node metastasis (1 paper, 2013). "Furthermore, Col5A2 has been associated with lymph node metastasis in lung adenorcarcinoma." (PMID 23574622, 2013).
metastatic melanoma (1 paper, 2025). A melanoma that has spread from its primary site to another anatomic site. "COL3A1, COL5A2 and VEGFA showed dataset-specific correlations; COL3A1 had strong associations with M1 macrophages, while VEGFA was positively correlated with CD4 T cells in metastatic melanomas." (PMID 40943183, 2025).
metastatic tumors (1 paper, 2025). "COL3A1, COL5A2, VCAN, CCND2, JAG2, and VTN showed consistent positive correlations with all three scores in both primary and metastatic tumors, suggesting their involvement in enhancing stromal support and recruiting immune cells." (PMID 40943183, 2025).
multiple sclerosis (1 paper, 2015). A progressive autoimmune disorder affecting the central nervous system resulting in demyelination. "COL1A1, COL3A1, COL5A1, and COL5A2 chains were induced significantly in active multiple sclerosis lesions and even more in inactive lesions." (PMID 26691002, 2015).
Myocardial fibrosis (1 paper, 2022). "In addition, transcript levels of a selected number of genes involved in myocardial fibrosis, namely, Ctgf (Ccn2), Postn, Col1a1, Col5a2, and Timp, quantified by RT-PCR, were also increased in the Pdgfra-Cre:LmnaF/F mouse hearts." (PMID 35891706, 2022).
nasopharyngeal carcinoma (1 paper, 2013). A carcinoma arising from the nasopharyngeal epithelium. "miR-29 targeted several extracellular matrix genes including COL1A2, COL3A1 and COL5A2, and has been validated in nasopharyngeal carcinomas and HTM (human trabecular meshwork) cells." (PMID 24079748, 2013).
oesophageal cancer (1 paper, 2023). "The top GPR176-correlated genes (PDPH, KIREL1, CLEC12A-AS1, CERCAM, IKBIP, LOX, COL5A2 and ELF3) were more highly expressed in oesophageal cancer than in normal tissue (p < 0.05), but the converse was true for C9orf152 and MT-TP (p < 0.05)." (PMID 37584712, 2023).
oral candidiasis (1 paper, 2022). Infection of the mucosal lining of the mouth with the fungus Candida albicans. "Also, the expression of MMP1, MMP10, COL5A2, SERPINB4, and CRABP2 was increased under both conditions, confirming that oral candidiasis may drive OSCC progression events in vivo." (PMID 35089096, 2022).
osteoarthritis (1 paper, 2022). A noninflammatory degenerative joint disease occurring chiefly in older persons, characterized by degeneration of the articular cartilage, hypertrophy of bone at the margins and changes in the synovial membrane. "Moreover, COL5A2 and COL6A1 were also demonstrated as upregulated genes associated with a pathological process of subchondral bone in osteoarthritis." (PMID 35831853, 2022).
ovarian tumors (1 paper, 2024). "Interestingly, we have previously reported CD2 and COL5A2 in a single gene signature for immune subtyping of desert, excluded, and inflamed ovarian tumors, suggesting that underlying biological mechanisms behind immune TME formation can be at least in part shared among tumors in different organs." (PMID 38397409, 2024).
pheochromocytoma (1 paper, 2021). "In conclusion, we found that the inactivation of pVHL in pheochromocytoma led to the up-regulation of the seven novel genes, such as CTGF, SDCBP, CYR61, COL3A1, COL1A1, COL5A2, and SERPINE1." (PMID 33828526, 2021).
pulmonary neuroendocrine neoplasms (1 paper, 2023). "In a recent study, the up-regulation of six fibrogenic genes (COL5A2, COL1A2, COL3A1, ITGA5, ITGB1, and ITGB1) in pulmonary neuroendocrine carcinoma and the down-regulation of pulmonary neuroendocrine neoplasms were strongly related to no metastasis and overall survival." (PMID 37047300, 2023).
renal cell carcinoma (1 paper, 2021). "A high expression of COL5A2 is associated with metastasis in renal cell carcinoma." (PMID 34503278, 2021).
serous ovarian cancers (1 paper, 2024). "A related study has shown that COL3A1 and COL5A2 were top hub genes related to the stage of serous ovarian cancers." (PMID 39518852, 2024).
systemic sclerosis (1 paper, 2023). A chronic disorder, possibly autoimmune, marked by excessive production of collagen which results in hardening and thickening of body tissues. "COL5A2 is modulated by TGF-βs and is highly related to human systemic sclerosis and IPF." (PMID 37798725, 2023).
tendinopathies (1 paper, 2018). "Using quantitative real-time PCR (qRT-PCR), the collagens Col1A1, Col3A1 and Col5A2 were found to be significantly upregulated in the tendinopathies and chronic ruptures compared to the intact control and the acute ruptured tendons." (PMID 29385715, 2018).
thoracic aortic aneurysm (1 paper, 2022). An aneurysm formed in the wall of the proximal portion of the descending aorta proceeding from the arch of the aorta. "One patient carried a CNV disrupting the COL3A1 and COL5A2 genes (vascular or hypermobility type of Ehlers–Danlos syndrome), and another patient a CNV in MYH11 (familial thoracic aortic aneurysms and dissections)." (PMID 35743335, 2022).
tongue cancer (1 paper, 2021). A malignant neoplasm affecting the tongue. "The up-regulation of COL5A2 is correlated with a poor prognosis in tongue cancer, a finding that was consistent with ours." (PMID 33739392, 2021).